FAM107B (family with sequence similarity 107 member B)
Synonyms: C10orf45; FLJ45505; MGC11034; HITS
Tractability: PROTAC: ubiquitination databases record sites on it; its protein half-life has been measured.
Gene: Protein-coding gene on chromosome 10 (14,518,557 to 14,774,897, reverse strand). Ensembl gene ENSG00000065809.
Subcellular location (Human Protein Atlas): Nucleoplasm; Golgi apparatus
Gene Ontology:
Cellular component: nucleoplasm
Genetic constraint (gnomAD): Loss-of-function variants: 21 observed, 33.38 expected, observed/expected ratio (o/e) 0.63, 90% interval 0.44 to 0.91. The upper end of that interval is the gene's LOEUF score, 0.91, which puts it in group 3 of 6, group 1 being the genes least tolerant of losing a copy. Missense variants: 452 observed, 396.63 expected, observed/expected ratio (o/e) 1.14, 90% interval 1.05 to 1.23. Synonymous variants: 157 observed, 149.88 expected, observed/expected ratio (o/e) 1.05, 90% interval 0.92 to 1.2.
Homologues: Orthologues: chimpanzee FAM107B (99% identical), macaque FAM107B (95% identical), dog FAM107B (81% identical), rat Fam107b (81% identical), mouse Fam107b (80% identical), rabbit FAM107B (80% identical), guinea pig Fam107b (46% identical), tropical clawed frog fam107b (39% identical), zebrafish fam107b (34% identical), Drosophila melanogaster CG9328 (16% identical). Paralogues in human: FAM107A (24% identical).
Diseases named in the same sentence as FAM107B in open-access papers:
FAM107B is named in the same sentence as 16 diseases in open-access papers, as found by Europe PMC text mining. Sharing a sentence is not in itself a finding about the gene and the disease. The quoted sentences say what the papers report.
deafness (1 paper, 2015). An inherited or acquired condition characterized by the complete loss of the ability to hear from one or both ears. "A mutation in another mouse nonessential gene, FAM107B, also was recently reported to display a deafness phenotype." (PMID 26301634, 2015).
leukemia (1 paper, 2024). A malignant (clonal) hematologic disorder, involving hematopoietic stem cells and characterized by the presence of primitive or atypical myeloid or lymphoid cells in the bone marrow and the blood. "Mutations in PKCθ have been detected in lymphomas and leukemias, including 2 fusion proteins (FAM107B-PRKCQ and PTGIS-PRKCQ, respectively), with two additional fusion proteins being detected in breast and ovarian cancers." (PMID 38752473, 2024).
cancer (5 papers, 2014 to 2023). A tumor composed of atypical neoplastic, often pleomorphic cells that invade other tissues. "After S100A4 knockdown in cancer cells, certain genes that inhibit proliferation and migration (e.g., FAM107B and E-cadherin) were upregulated, while those genes that normally promote proliferation and migration (e.g., NF-κB, p65 and MMP2) were downregulated." (PMID 29342841, 2018). "The expression of FAM107A and FAM107B proteins is prominent in neural cells, whereas their expression is downregulated in cancer cells." (PMID 24748967, 2014). "Our findings indicated that the interactions between CD8T cells and other cellular components play a significant role in certain cancer-related signal pathways, and the mutations of FAM107B and TUBA4A were not important factors in the development of PTC." (PMID 37861558, 2023).
tumor (3 papers, 2014 to 2023). "In addition, we found that FAM107B expression was remarkably downregulated while TUBA4A expression was remarkably upregulated in tumor group in comparison with normal group." (PMID 37861558, 2023).
FAM107B also shares sentences with these, for which no sentence is quoted: Alzheimer disease (2 papers); Parkinson disease (2); breast (1); breast carcinoma (1); ductal carcinoma in situ in (1); gastric cancer (1); Huntington disease (1); lymphoma (1); neurodegenerative disease (1); ovarian carcinoma (1); squamous carcinoma (1); tubular adenoma (1).